ENSG00000277994
Gene: Miscellaneous RNA gene on chromosome 12 (53,965,965 to 53,966,061, forward strand). Ensembl gene ENSG00000277994.
Gene Ontology:
Biological process: heterochromatin formation
Homologues: Orthologues: mouse Gm55342 (81% identical).